TRPM6 (transient receptor potential cation channel subfamily M member 6)
Description:
Bifunctional protein that combines an ion channel with an intrinsic kinase domain, enabling it to modulate cellular functions either by conducting ions through the pore or by phosphorylating downstream proteins via its kinase domain. Crucial for Mg(2+) homeostasis. Has an important role in epithelial Mg(2+) transport and in the active Mg(2+) absorption in the gut and kidney. However, whether TRPM6 forms functional homomeric channels by itself or functions primarily as a subunit of heteromeric TRPM6-TRPM7 channels, is still under debate. [TRPM6 kinase, cleaved form]: The C-terminal kinase domain can be cleaved from the channel segment in a cell-type-specific fashion. The cleaved kinase fragments can translocate to the nucleus, and bind chromatin-remodeling complex proteins to ultimately phosphorylate specific Ser/Thr residues of histones known to be functionally important for cell differentiation and development.
Synonyms: CHAK2; FLJ22628; HMGX; HOMG; HOMG1; HSH
Tractability: Small molecule: a high-quality ligand is known; it belongs to a druggable protein family. Antibody: UniProt places it where antibodies can reach, with high confidence; its Gene Ontology location is reachable by antibodies, with high confidence; UniProt predicts a signal peptide or a membrane-spanning region. PROTAC: ubiquitination databases record sites on it; a small molecule that binds it is known.
Target class: Voltage-gated ion channel; Ion channel; Transient receptor potential channel
Gene: Protein-coding gene on chromosome 9 (74,722,495 to 74,888,094, reverse strand). Ensembl gene ENSG00000119121.
Subcellular location: Cell membrane; Apical cell membrane; Nucleus (TRPM6 kinase, cleaved form)
Pathways (Reactome):
Transport of small molecules: TRP channels
Gene Ontology:
Molecular function: calcium ion transmembrane transporter activity; magnesium ion transmembrane transporter activity; protein binding; protein serine kinase activity; protein serine/threonine kinase activity; calcium channel activity; protein kinase activity; ATP binding; monoatomic cation channel activity
Biological process: calcium ion transmembrane transport; magnesium ion transmembrane transport; response to toxic substance; calcium ion transport; monoatomic cation transmembrane transport; protein tetramerization
Cellular component: apical plasma membrane; nucleus; plasma membrane; brush border membrane; membrane
Genetic constraint (gnomAD): Loss-of-function variants: 98 observed, 234.52 expected, observed/expected ratio (o/e) 0.42, 90% interval 0.35 to 0.49. The upper end of that interval is the gene's LOEUF score, 0.49, which puts it in group 2 of 6, group 1 being the genes least tolerant of losing a copy. Missense variants: 2,009 observed, 2,427.2 expected, observed/expected ratio (o/e) 0.83, 90% interval 0.8 to 0.86. Synonymous variants: 855 observed, 868.58 expected, observed/expected ratio (o/e) 0.98, 90% interval 0.93 to 1.04.
Homologues: Orthologues: chimpanzee TRPM6 (99% identical), macaque TRPM6 (96% identical), dog TRPM6 (86% identical), pig TRPM6 (85% identical), rabbit TRPM6 (82% identical), mouse Trpm6 (78% identical), rat Trpm6 (78% identical), guinea pig TRPM6 (73% identical), tropical clawed frog trpm6 (63% identical), zebrafish trpm6 (45% identical), Drosophila melanogaster Trpm (30% identical), Caenorhabditis elegans gon-2 (27% identical), and 3 more. Paralogues in human: TRPM7 (50% identical), TRPM3 (37% identical), TRPM1 (35% identical), TRPM2 (19% identical), TRPM4 (16% identical), TRPM5 (16% identical), TRPM8 (14% identical).
Diseases named in the same sentence as TRPM6 in open-access papers:
TRPM6 is named in the same sentence as 100 diseases in open-access papers, as found by Europe PMC text mining. Sharing a sentence is not in itself a finding about the gene and the disease. The quoted sentences say what the papers report.
Hypomagnesemia (76 papers, 2010 to 2026). An abnormally decreased magnesium concentration in the blood. "Homozygous mutations of TRPM6 cause severe hypomagnesemia, and hypocalcemia in newborns with seizures and tetany." (PMID 39803707, 2025). "Severe hypomagnesemia is associated with reduced magnesium absorption by downregulating TRPM6-mediated magnesium influx into Caco-2 cells." (PMID 40564302, 2025). "In humans, mutations of the TRPM6/7 proteins are linked to hypomagnesemia and other conditions, including macrothrombocytopenia and trigeminal neuralgia." (PMID 40003994, 2025). "Loss-of-function mutations in the TRPM6 gene cause hypomagnesemia with secondary hypocalcemia (HSH; OMIM: 602014)." (PMID 39266724, 2025). "It has been reported that patients with hypomagnesemia with secondary hypocalcemia present the S141L mutation, which causes a decrease in the expression of TRPM6 at the plasma membrane." (PMID 39108834, 2024). "PPIs are thought to cause hypomagnesemia by reducing the active magnesium absorption that occurs via transient receptor potential melastatin 6 and 7 (TRPM6/7)." (PMID 39114244, 2024). "Deletion of Trpm6 in mice is embryonic lethal, whereas humans with recessive mutations in TRPM6 develop early onset of hypomagnesemia and secondary hypocalcemia, further emphasizing the significance of Mg2+ reabsorption in the DCT." (PMID 38638279, 2024). "Insulin upregulates TRPM6 activity; thus, patients with lower insulin receptor activity are more susceptible to hypomagnesemia." (PMID 38511086, 2024). "Pathological variants of the TRPM6 gene have been linked to hypomagnesemia in patients with familial hypomagnesemia with secondary hypocalcemia." (PMID 37512002, 2023). "Accordingly, hypomagnesemia occurs in kidney-specific TRPM6-deficient mice due to renal magnesium wasting." (PMID 37072467, 2023). "We and others demonstrated that diuretics‐use and genetic variants (SNPs) in Mg2+ channel TRPM6 increase the risk for PPI‐induced hypomagnesemia." (PMID 35652564, 2022). "It has been shown that mutations of TRPM6 in humans is causative for hypomagnesemia with secondary hypocalcemia." (PMID 35216094, 2022). "Several forms of hereditary hypomagnesemia in humans have led to the identification of causative genes, including the transient receptor potential melastatin 6 (TRPM6) and cyclin M2 (CNNM2)." (PMID 35216094, 2022). "An autosomal dominant inherited variant ofKCNA1, which encodes the voltage-gated potassium channel (Kv1.1) colocalized with TRPM6, reported as a rare cause of isolated hypomagnesemia." (PMID 33155789, 2021). "Proton pump inhibitor use is a common cause of hypomagnesemia, presumably due to impaired intestinal absorption, caused by inhibition of selective channels (TRPM-6) in the duodenum by the proton pump inhibitor." (PMID 33544331, 2021). "Familial hypomagnesemia with secondary hypocalcemia is a rare genetic cause of hypomagnesemia, due to variants in the transient receptor potential melastatin 6 (TRPM6) genes." (PMID 32302086, 2021). "Trpm6, encoding transient receptor potential melastatin-related 6 (TRPM6), is mutated in patients with recessive hypomagnesemia with secondary hypocalcemia." (PMID 34140503, 2021). "Variants in the gene for the distal convoluting tubules and colon specific apical Mg2+ channel, the transient receptor potential melastatin 6 (TRPM6) gene, cause the most profound genetic hypomagnesemia." (PMID 32302086, 2021). "Hypomagnesemia in patients with familial hypomagnesemia with secondary hypocalcemia has been attributed to mutations of TRPM6." (PMID 30987399, 2019). "Mutations in the gene for the DCT- and colon-specific apical Mg2+ channel, TRPM6, cause the most profound genetic hypomagnesemia." (PMID 27234911, 2017). "We present the clinical follow-up findings of a pediatric HSH case due to a novel mutation in the TRPM6 gene and highlight the need for molecular genetic analysis in inbred or familial cases with hypomagnesemia." (PMID 26759217, 2016).
Hypomagnesemia (continued). "Mutations in TRPM6 occur in the rare autosomal-recessive disease hypomagnesemia with secondary hypocalcemia (HSH) in human." (PMID 27757375, 2016). "A significant association was observed between common variants of TRPM6 and hypomagnesemia, with a specific T allele of rs11144134 in TRPM6 associated with higher femoral neck and lumbar spine BMD." (PMID 27757375, 2016). "In the present work, we focussed on the closest TRPM7 relative, TRPM6, because loss-of-function mutations in TRPM6 cause hypomagnesemia (low Mg2+ blood levels) in human infants thought to mainly result from renal Mg2+ wasting." (PMID 27991852, 2016). "We found that, similar to humans with mutations in the TRPM6 gene, Trpm6-deficient mice developed hypomagnesemia." (PMID 27991852, 2016). "Human infants with loss-of-function mutations in TRPM6 develop severe hypomagnesemia with secondary hypocalcemia (HSH), indicating that TRPM6 is important for Mg2+ (re-) absorption in the intestine and in kidneys." (PMID 25106481, 2015). "Loss-of-function mutations of TRPM6 cause intestinal Mg2+ malabsorption and renal Mg2+ wasting, as evidenced in patients suffering from hypomagnesemia with secondary hypocalcemia (HSH, OMIM #602014)." (PMID 25774985, 2015). "In contrast, TRPM6 is believed to be responsible for systemic Mg2+ regulation by mediating Mg2+ (re) absorption, as a mutation in the TRPM6 gene leads to an autosomal recessive form of familial hypomagnesemia with secondary hypocalcemia." (PMID 25277194, 2014). "Interestingly, chronic PPI users with SNPs in TRPM6 have an increased risk of developing hypomagnesemia." (PMID 39266724, 2025). "Considering both TRPM proteins are co-expressed highly in the colon and DCT, it is likely that in both cases the underlying mechanism of the hypomagnesemia is intestinal malabsorption and renal wasting caused by decreased functioning of TRPM6/TRPM7 heterotetramers." (PMID 39099563, 2024). "Indeed, intestine‐specific disruption of Trpm6 in mice caused severe hypomagnesemia due to a defect in intestinal Mg2+ absorption." (PMID 35652564, 2022). "Current evidence shows that carriers of TRPM6/7 mutations and SNPs in TRPM6 could be at risk of developing hypomagnesemia during chronic PPI use." (PMID 36514145, 2022). "TRPM6 variant is a cause of profound hypomagnesemia with secondary hypocalcemia." (PMID 32302086, 2021). "The critical role of TRPM6 for systemic Mg homeostasis became evident when loss-of-function mutations in the TRPM6 gene were discovered in patients with a rare form of hereditary hypomagnesemia (hypomagnesemia with secondary hypocalcemia, HSH)." (PMID 29912157, 2018). "It has been postulated that individuals carrying heterozygous mutations of TRPM6/7 may be at especially high risk, as evidenced from observations that people with homozygous mutations of TRPM6 manifest severe hypomagnesemia." (PMID 25268962, 2014). "In patients with isolated dominant hypomagnesemia, the FXYD2b abnormality causes inadequate Na,K-ATPase-energized transcellular magnesium transport in the distal convoluted tubule via the apical Mg2+ channel TRPM6 and the Na+-Mg2+ exchanger at the basolateral site." (PMID 40428357, 2025). "Although rare, chronic use of proton pump inhibitors (PPIs) can cause hypomagnesemia due to impaired intestinal absorption, mainly attributed to reduced transcellular transport of magnesium via transient receptor potential melastatin 6 (TRPM6) and 7 (TRPM7) channels." (PMID 38222324, 2024). "In contrast, the Mg2+‐permeable transient receptor potential cation channel subfamily M member 6 (TRPM6) was identified as a candidate gene for Mg2+ uptake after screening families with autosomal recessive hypomagnesemia." (PMID 39803707, 2025). "This subsequently leads to decreased TRPM-6 activity, reducing magnesium reabsorption in the distal nephron and leading to hypomagnesemia." (PMID 40868117, 2025).
Hypomagnesemia (continued). "Patients with diabetes mellitus also frequently develop hypomagnesemia, which has been attributed to diabetic hyperfiltration and the interaction of insulin in downregulating TRPM6 activity and expression." (PMID 40740723, 2025). "Cisplatin induces magnesium wasting of the kidneys via downregulation of TRPM6/7 channels and damage to the distal tubules, resulting in hypomagnesemia that exacerbates kidney injury." (PMID 41154367, 2025). "These phenotypes are reminiscent of hypomagnesemia with secondary hypocalcemia (HSH, MIM #602 014) caused by bi-allelic variants in TRPM6." (PMID 39099563, 2024). "The findings revealed that dietary magnesium restriction and hypomagnesemia increase TRPM6 expression to enhance Mg absorption." (PMID 37512002, 2023). "They reported that single nucleotide polymorphism in TRPM6 (rs3750425 and rs2274924) increases the risk for PPI-induced hypomagnesemia approximately 5.8-fold." (PMID 35178215, 2022). "The confirmed drug-target interactions suggest an attenuation of pulmonary vascular remodeling (inhibition of PDE10A), modulation of Hepatitis C (HCV) viral response (inhibition of PKN2), and hypomagnesemia (inhibition of TRPM6)." (PMID 35551258, 2022). "TRPM6 is very important for Mg2+ uptake; TRPM6P1017R mutation impairs channel activity of TRPM6/TRPM7 heteromers, which leads to hypomagnesemia." (PMID 35813831, 2022). "TRPM6 is known to be related to two pathways (e.g., CREB Pathway and Ion channel transport) and associated with a disease named Hypomagnesemia." (PMID 31552087, 2019). "Hypomagnesemia 1 (HOMG1) is an extremely rare disease with autosomal recessive inheritance that is caused by mutations in the transient receptor potential melastatin 6 gene (TRPM6)." (PMID 30911400, 2019). "Molecular mechanisms underlying these side effects have been attributed to abnormal function of TRPM6, phenomena that were first described in patients carrying a mutation in the EGF gene and who have severe hypomagnesemia and cognitive disability." (PMID 30995736, 2019). "Inhibition of these processes with EGFR inhibitors decreases TRPM6 activity and reduces Mg2+ influx into cells, promoting Mg2+ excretion in the kidney with resultant Mg2+ wasting and hypomagnesemia." (PMID 30995736, 2019). "PPIs induce hypomagnesemia through decreasing active Mg absorption via transient receptor potential melastatin-6 and -7 (TRPM6/7) in the small intestine." (PMID 29969455, 2018). "Surviving heterozygous TRPM6 knockout mice exhibited mild hypomagnesemia, consistent with TRPM6′s reported role in magnesium homeostasis." (PMID 29142255, 2017). "Such TRP channelopathies include night blindness (TRPM1), progressive familial heart block type I (TRPM4), hypomagnesemia with secondary hypocalcemia (TRPM6), and autosomal dominant polycystic kidney disease (TRPP2), to name a few." (PMID 26490951, 2016). "Reduced TRPM6 channel activity results in a clinically relevant hypomagnesemia due to renal Mg2+ wasting." (PMID 25774985, 2015). "Because insulin and EGF stimulate TRPM6 function, patients with diabetes mellitus type 2 or users of EGFR inhibitors are at risk to develop hypomagnesemia." (PMID 25774985, 2015). "Hypocalciuria was secondary to enhanced passive calcium reabsorption in the proximal tubule and hypomagnesemia was secondary to the downregulation of magnesium channels (TRPM6) in the DCT." (PMID 23031616, 2012). "Homozygous deletion of TRPM6 in mice is lethal, while heterozygous deletion of TRPM6 results in mild hypomagnesemia, a deficit that cannot be compensated for by a magnesium-rich diet." (PMID 21420431, 2011). "This is associated with inhibition of the Transient Receptor Potential Cation Channel, Subfamily M, Member 6 -TRPM6 channel, which leads to urinary magnesium leakage and hypomagnesemia, subsequently stopping PTH secretion and resulting in hypocalcemia and hypocalciuria." (PMID 41751411, 2026).
Hypomagnesemia (continued). "Hypomagnesemia is primarily due to downregulation of the TRPM6 channel, expressed in the DCT, though some patients may have normomagnesemia, often associated with milder symptoms." (PMID 40777730, 2025). "TRPM6 heterozygous deletions are viable but result in hypomagnesemia." (PMID 40003994, 2025). "Furthermore, a magnesium-deficient diet led to hypomagnesemia and aggravated dextran sodium sulfate (DSS)-induced colitis, which was accompanied by compromised intestinal magnesium absorption and reduced TRPM6 expression." (PMID 40564302, 2025). "Thus, the activity of TRPM6 has been indicated to be dependent on the expression of TRPM7, while mutations in TRPM6 appear to induce hypomagnesemia with secondary hypocalcemia." (PMID 39614204, 2024). "Interestingly, TRPM6 was included in a group of kidney-specific magnesiotropic proteins involved in the autosomal-recessive disorder hypomagnesemia with secondary hypocalcemia (HSH)." (PMID 36979634, 2023). "Genetic studies also confirm the essential role of TRPM6 in PPI‐induced hypomagnesemia." (PMID 35652564, 2022). "The reduced TRPM6 expression and hypomagnesemia can hence not be explained with a loss of TRPM6 expressing DCT epithelium." (PMID 33200256, 2021). "Likewise, mutations in TRPM6 and FXYD2 cause renal tubulopathies with magnesium wasting and hypomagnesemia." (PMID 33200256, 2021). "Indeed, heterozygous deletion of TRPM6 in mice results in hypomagnesemia whereas serum calcium levels were unaffected." (PMID 33884443, 2021). "Here, we describe a pediatric HOMG1 case with novel compound heterozygous mutations of TRPM6 (c.1483 C > T [p.Gln495*] and c.2715del [p.Trp905*]) in a 2-month-old boy who developed refractory seizures due to hypomagnesemia with secondary hypocalcemia." (PMID 30911400, 2019). "We previously reported the co-localization of NCC and transient receptor potential cation channel subfamily M member 6 (TRPM6) in the kidney, and the down-regulation of magnesium channel TRPM6 in GS may explain hypomagnesemia." (PMID 30319542, 2018). "Accordingly, the significant reduction in the DCT plasma membrane area and TRPM6 downregulation could participate in the pathogenesis of hypomagnesemia." (PMID 29378538, 2018). "One of these is caused by mutations in TRPM6, which encodes the DCT-specific apical Mg2+ transporter TRPM6, resulting in an isolated hypomagnesemia (i.e. no other symptoms except secondary to the hypomagnesemia)." (PMID 27234911, 2017). "Heterozygous TRPM6 knockout mice exhibited mild hypomagnesemia." (PMID 27757375, 2016). "Human TRPM6 also give rise to hypomagnesemia with secondary hypocalcemia (HSH)." (PMID 25542231, 2015). "Non-functional mutations of TRPM6 are responsible for a primary disorder termed hypomagnesemia with secondary hypocalcemia." (PMID 21420431, 2011). "Furthermore, regarding hypomagnesemia, a link has been suggested with the transient receptor potential melastatin (TRPM) 6 cation channel present in the distal tubules of the kidneys, and it has been reported that EGFR inhibitors cause downregulation of TRPM6." (PMID 40755575, 2025). "Moreover, prolonged omeprazole administration induced hypomagnesemia, chronic small intestinal inflammation, and villous atrophy, and hyper-oxidation of TRPM6 in PPIH rats might have been induced by chronic small intestinal inflammation." (PMID 36110961, 2022). "Moreover, because hypomagnesemia may per se stimulate TRPM6 expression, it is difficult to isolate the effects of hypomagnesemia from those of diabetes itself." (PMID 33396570, 2020). "However, in familial hypomagnesemia with secondary hypocalcemia due to mutations in TRPM6, hypokalemia has not been reported, arguing against a substantial contribution of hypomagnesemia to decreased potassium levels." (PMID 31517149, 2019).